KCNC1 (potassium voltage-gated channel subfamily C member 1)
Description:
Voltage-gated potassium channel that opens in response to the voltage difference across the membrane and through which potassium ions pass in accordance with their electrochemical gradient. The mechanism is time-dependent and inactivation is slow (By similarity). Plays an important role in the rapid repolarization of fast-firing brain neurons (By similarity). Can form functional homotetrameric channels and heterotetrameric channels that contain variable proportions of KCNC2, and possibly other family members as well (By similarity). Contributes to fire sustained trains of very brief action potentials at high frequency in pallidal neurons (By similarity).
Synonyms: Kv3.1; EPM7; KV4; NGK2
Tractability: Small molecule: an approved drug acts on it; a structure with a bound ligand is known; it belongs to a druggable protein family. Antibody: UniProt places it where antibodies can reach, with high confidence; its Gene Ontology location is reachable by antibodies, with high confidence; UniProt predicts a signal peptide or a membrane-spanning region. PROTAC: its protein half-life has been measured.
Target class: Potassium channels; Ion channel; Voltage-gated ion channel; Voltage-gated potassium channel
Gene: Protein-coding gene on chromosome 11 (17,734,774 to 17,856,804, forward strand). Ensembl gene ENSG00000129159.
Subcellular location: Cell membrane; Cell projection, axon; Presynaptic cell membrane
Subcellular location (Human Protein Atlas): Nuclear membrane; Nucleoplasm; Cytosol; Vesicles
Pathways (Reactome):
Neuronal System: Voltage gated Potassium channels
Gene Ontology:
Molecular function: protein binding; voltage-gated potassium channel activity; delayed rectifier potassium channel activity; gated channel activity; kinesin binding; monoatomic ion channel activity; transmembrane transporter binding; voltage-gated monoatomic ion channel activity involved in regulation of presynaptic membrane potential
Biological process: protein tetramerization; action potential; potassium ion transmembrane transport; potassium ion transport; cellular response to xenobiotic stimulus; cerebellum development; corpus callosum development; globus pallidus development; monoatomic ion transport; optic nerve development; positive regulation of monoatomic ion transmembrane transport; positive regulation of potassium ion transmembrane transport; protein homooligomerization; regulation of monoatomic ion transmembrane transport; regulation of potassium ion transmembrane transport; regulation of presynaptic membrane potential; response to amine; response to auditory stimulus; response to fibroblast growth factor; response to light intensity; response to nerve growth factor; response to potassium ion; response to toxic substance; transmembrane transport
Cellular component: plasma membrane; voltage-gated potassium channel complex; axon terminus; dendrite membrane; neuronal cell body membrane; postsynaptic membrane; presynaptic membrane; axolemma; axon; calyx of Held; cell surface; dendrite; membrane; neuron projection membrane; neuronal cell body
Genetic constraint (gnomAD): Loss-of-function variants: 8 observed, 39.81 expected, observed/expected ratio (o/e) 0.2, 90% interval 0.12 to 0.36. The upper end of that interval is the gene's LOEUF score, 0.36, which puts it in group 1 of 6, group 1 being the genes least tolerant of losing a copy. Missense variants: 408 observed, 812.19 expected, observed/expected ratio (o/e) 0.5, 90% interval 0.46 to 0.55. Synonymous variants: 352 observed, 356.58 expected, observed/expected ratio (o/e) 0.99, 90% interval 0.9 to 1.08.
Gene-disease validity (ClinGen):
ClinGen rates the evidence that KCNC1 causes each of these diseases.
complex neurodevelopmental disorder (autosomal dominant): Definitive. A disorder that involves more than one phenotype associated with the central nervous system, including but not limited to intellectual disability, autism, and seizures (epilepsy).
progressive myoclonus epilepsy (autosomal dominant): Definitive. A rare group of disorders characterized by the development of myoclonic and tonic-clonic epileptic seizures associated with progressive degeneration of the nervous system.
Homologues: Orthologues: chimpanzee KCNC1 (100% identical), dog KCNC1 (99% identical), mouse Kcnc1 (99% identical), rat Kcnc1 (99% identical), guinea pig KCNC1 (99% identical), macaque KCNC1 (99% identical), pig KCNC1 (99% identical), zebrafish kcnc1a (79% identical), zebrafish kcnc1b (76% identical), rabbit KCNC1 (71% identical), tropical clawed frog kcnc1 (49% identical). Paralogues in human: KCNC3 (74% identical), KCNC4 (69% identical), KCNC2 (68% identical), KCNB2 (32% identical), KCNA4 (31% identical), KCNA3 (30% identical), KCNA2 (29% identical), KCNA6 (29% identical), KCNA1 (29% identical), KCNA5 (29% identical), KCNA7 (29% identical), and 19 more.
Diseases named in the same sentence as KCNC1 in open-access papers:
KCNC1 is named in the same sentence as 57 diseases in open-access papers, as found by Europe PMC text mining. Sharing a sentence is not in itself a finding about the gene and the disease. The quoted sentences say what the papers report.
epilepsy (28 papers, 2013 to 2026). A brain disorder characterized by episodes of abnormally increased neuronal discharge resulting in transient episodes of sensory or motor neurological dysfunction, or psychic dysfunction. "Inactivating mutations in the KCNC1 gene lead to forms of epilepsy and a decline in the expression of the Kv3.1 channel is involved in age‐related hearing loss." (PMID 38725150, 2024). "Mutations in KCNC1 are linked to various neurological disorders, including epilepsy, developmental delay, and ataxia." (PMID 39434833, 2024). "KCNC1 encodes a subunit of the Kv3 voltage–gated potassium channels and is associated with various human diseases, including ataxia, epilepsy, and developmental delay." (PMID 37715200, 2023). "Mutations in KCNC1 can cause severe neurological dysfunction, including intellectual disability, epilepsy, and ataxia." (PMID 33735526, 2021). "The voltage‐gated Kv3.1/KCNC1 channel is expressed in fast‐spiking GABAergic inhibitory interneurons and principal neurons of the ascending auditory pathway and dysfunction of this channel leads to epilepsy and age‐related hearing loss." (PMID 38725150, 2024). "The small molecule Kv3 activator RE01 partially rescued electrophysiological defects, suggesting that pharmacological activation of Kv3.1 activity may offer a treatment option for KCNC1-associated epilepsy patients." (PMID 39434833, 2024). "Gain-of-function (GOF) de novo pathogenic variants in KCNC1 and KCNC2, encoding Kv3.1 and Kv3.2 respectively, cause several types of epilepsy including developmental and epileptic encephalopathy (DEE)." (PMID 39881864, 2024). "The first group is the studies that described the generation of patient-specific iPSC lines that carry genetic variants in genes associated with epilepsy, such as SCN1A, GNB5, LGI1, GRIN2A, KCNC1, or KCNA2." (PMID 36552721, 2022). "For example, de novo dominant negative mutations in voltage-gated potassium channel subfamily C member 1 (KCNC1) were identified in epilepsy patients." (PMID 33853504, 2021). "Kcnc1-related disorders include a form of epilepsy and ataxia." (PMID 38255294, 2024). "Pathogenic variants of KCNC1 are associated with severe neurological phenotypes, including myoclonic epilepsy, ataxia, intellectual disability without epilepsy, and developmental and epileptic encephalopathy." (PMID 39881864, 2024).
Ataxia (14 papers, 2013 to 2025). Ataxia refers to impaired coordination of voluntary muscle movement. "KCNC1 encodes a voltage-gated potassium channel expressed in inhibitory neurons, and mutations in the gene cause progressive myoclonus epilepsy and ataxia." (PMID 35299674, 2022). "In mouse models, mice that lacked two potassium voltage-gated channels (Kv3.1 encoded by KCNC1 as well as Kv3.3) exhibited tremor, ataxia, and alcohol hypersensitivity, as well as altered circadian rhythms." (PMID 25161819, 2014). "Indeed, a recurrent pathogenic heterozygous sequence variant in KCNC1 (gene MIM number 176258) was identified as a cause of childhood‐onset progressive myoclonic epilepsy variability associated with ataxia, tonic–clonic seizures, learning disabilities, and mild cognitive decline." (PMID 38725150, 2024). "KCNC1‐related progressive myoclonus epilepsy (EPM7) is a rare disorder causing seizures, myoclonus, and ataxia." (PMID 40765656, 2025). "Mutations in KCNC1, KCNC2 and KCNC3 have been implicated in several neurological and psychiatric disorders such as epilepsy, ataxia, and neurodevelopmental disorders (NDD) such as ASD and SCZ." (PMID 39411003, 2024). "Mutations in KCNC1 are associated with a specific type of PME, myoclonus epilepsy and ataxia due to potassium channel mutation (MEAK)." (PMID 39411003, 2024). "In addition, defects in various potassium channels (KCNC1, KCTD7) have been associated with PMEs such as myoclonus epilepsy and ataxia due to potassium channel mutations (MEAK) and KCTD7-related PME (EPM3)." (PMID 39156922, 2024). "Knocking out KCNC1 in KCNC1-mutant mice has been reported to lead to myopathy and ataxia." (PMID 35299674, 2022).
progressive myoclonus epilepsy (8 papers, 2015 to 2025). "A recurrent de novo mutation, c.959G>A (p.Arg320His), in KCNC1 was identified as a new major cause for progressive myoclonus epilepsies (PMEs)." (PMID 33718116, 2020). "Mutations in KCNC1 have been reported as the driving cause for progressive myoclonus epilepsies." (PMID 30208958, 2018). "Indeed, different de novo mutations in KCNC1 have been reported to display a wide variety of progressive myoclonus epilepsy." (PMID 28049438, 2017). "The de novo mutations in KCNC1, which encodes KV3.1 channels, have been also found to expand phenotypic spectra of this channel to progressive myoclonus epilepsy." (PMID 28049438, 2017).
Alzheimer disease (5 papers, 2016 to 2023). A progressive, neurodegenerative disease characterized by loss of function and death of nerve cells in several areas of the brain leading to loss of cognitive function such as memory and language. "A reduction of gamma activity is observed in patients with Alzheimer’s disease, whereas an increase is found in patients with ADHD, implicating a role of the KCNC1 gene in ADHD." (PMID 29176790, 2017).
developmental and epileptic encephalopathy (5 papers, 2024 to 2026). An epilepsy associated with developmental impairment that may be due to either the underlying etiology or the superimposed epileptic activity, or both. "BACKGROUND: Pathogenic KCNC1 mutations (encoding Kv3.1 potassium channels) drive heterogeneous neurological disorders, ranging from progressive myoclonus epilepsy-ataxia (MEAK) to developmental/epileptic encephalopathies (DEE) and global developmental delay." (PMID 41622135, 2026).
channelopathies (4 papers, 2020 to 2026). "The underlying channelopathy pathway accounted for 46.7% (7/15) of the monogenic variants, including ion channel genes (SCN1A, KCTD7, KCNC1, CACNA1A, KCNMA1) and ligand-gated ion channel genes (GABRA1, GABRG2)." (PMID 36034301, 2022).
Epileptic encephalopathy (2 papers, 2015 to 2026). A condition in which epileptiform abnormalities are believed to contribute to the progressive disturbance in cerebral function. "In this study, we generate a novel transgenic mouse model with conditional expression of the A421V pathogenic missense variant (Kcnc1-A421V/+ mice) to explore the specific physiological mechanisms of KCNC1 developmental and epileptic encephalopathy." (PMID 41705663, 2026). "Together, these results establish the specific impact of the recurrent Kv3.1-A421V variant on neuronal excitability and synaptic physiology across development to drive network dysfunction underlying KCNC1 epileptic encephalopathy." (PMID 41705663, 2026).
progressive myoclonic epilepsy 7 (2 papers, 2022 to 2024). "A frameshifting variant in the KCNC1 gene associated with progressive myoclonic epilepsy 7 (EPM7, ClinVar ID: 692088) causes premature termination at K457 (located within the ATM) and therefore deletes many of the residues involved in this T1/ C-terminal interaction." (PMID 35840580, 2022).
seminoma (2 papers, 2024). A radiosensitive malignant germ cell tumor found in the testis (especially undescended), and extragonadal sites (anterior mediastinum and pineal gland). "Another hypermethylated gene is KCNC1, whose downregulation was able to predict poor survival in seminoma patients and was suggested as a diagnostic biomarker as well as a therapeutic target after being identified through TCGA and confirmed seminoma cell lines." (PMID 38791003, 2024). "In seminoma, KCNC1 (Kv3.1) was hypermethylated which would inhibit its expression, and this was associated with poor overall survival in patients." (PMID 38976181, 2024).
glioma (1 paper, 2023). A benign or malignant brain and spinal cord tumor that arises from glial cells (astrocytes, oligodendrocytes, ependymal cells). "It should also be noted that the function of KCNC1, KCNT1, RIMS2, NECAP2, GNG5, SCAMP2, GNAI3 genes is also correlated with membrane function in low-grade gliomas." (PMID 37239411, 2023).
ischemia (1 paper, 2019). A hypoperfusion of the BLOOD through an organ or tissue caused by a PATHOLOGIC CONSTRICTION or obstruction of its BLOOD VESSELS, or an absence of BLOOD CIRCULATION. "Thereby, 4 h of ischemia was associated with a weakly diminished immunosignal of Kcnc1 in the ischemia-affected region, whereas Pvalb remained stable and also the Acan immunoreactivity robustly maintained towards the ischemic region." (PMID 31089963, 2019).
myoclonic epilepsy (1 paper, 2024). A group of epilepsy syndromes in which myoclonic seizures are a prominent feature. "Regarding KCNC1, a study conducted in 2016 found that 16 out of 84 clinically confirmed Progressive Myoclonic Epilepsy (PME) cases without clear genetic etiology had a monoallelic missense variant in the KCNC1 gene, c.959G > A (p.Arg320His), 13 of whom were unrelated." (PMID 38783211, 2024).
infection (2 papers, 2017 to 2022). The state of being infected such as from the introduction of a foreign agent such as serum, vaccine, antigenic substance or organism. "Of the genes participating in metal ion binding (MIB1, KAT6B, ITGA8, HBAC, KCNC1, and F13A), most were downregulated during the later stages of GCRV infection, whereas genes involved in protein ubiquitination (HERC1 and HERC4) were upregulated during the later stages of infection." (PMID 28906455, 2017).
KCNC1 also shares sentences with these, for which no sentence is quoted: schizophrenia (7 papers); Intellectual disability (6); cancer (4); depression (4); developmental delay (4); neuroblastoma (4); neurological disorders (4); Brugada syndrome (3); tumor (3); atrial fibrillation (2); cardiovascular diseases (2); heart failure (2); myoclonus epilepsy (2); spinocerebellar ataxia type 13 (2); Stroke (2); age (1); Anxiety (1); autosomal recessive disease (1); bipolar disorder (1); cardiac diseases (1); cognitive decline (1); colon cancer (1); congenital stationary night blindness (1); diabetes insipidus (1); episodic ataxia (1); experimental autoimmune encephalomyelitis (1); fragile X syndrome (1); hypertrophy (1); hypoxia (1); learning disabilities (1).
A further 14 diseases each share a sentence with KCNC1 in 1 paper.